CD4 (CD4 molecule)
Diseases named in the same sentence as CD4 in open-access papers (continued):
Sharing a sentence is not in itself a finding about the gene and the disease.
Arthritis (continued). "This is an interesting observation regarding that STAT3-regulated SOCS3 expression in CD4+ T cells has been shown to be elevated in a cohort of 161 treatment-naïve early arthritis patients and in PBMCs from patients with active RA." (PMID 34630419, 2021). "In terms of STAT3, its phosphorylation by nuclear PKM2 has recently been implicated to mediate the pathogenic phenotype of coronary artery disease macrophages, inflammatory lung epithelial cells, EAE Th17 cells, and CD4+ T cells in a model of arthritis." (PMID 34858390, 2021). "CD4+ T cells play a critical role in GPI-induced arthritis, and the effect of biological agents including anti-interleukin-6 (IL-6) receptor antibodies is similar to that found in RA patients." (PMID 34299252, 2021). "The ability to identify, manipulate and track specific cell populations is particularly useful in animal models, as has been shown in research examining the roles of autoreactive CD4 T cells in the development of early arthritis." (PMID 34380700, 2021). "These two clusters share features that include T cell receptor signaling, the involvement of monocytes and CD4+ T cells, enrichment of Rel and NFKB transcription factors and association with arthritis and leprosy." (PMID 33763080, 2021). "Blocking IL-17A or TNF along with the depletion of CD4+ T cells produced protective effects against the development of arthritis with modulation of TRAP5b." (PMID 34067675, 2021). "1.5 x106 murine CD4+ OVA-TCR-Tregs or OVA-TCR-FOXP3-T cells suppressed methylated BSA induced arthritis in C57BL/6 mice following a rechallenge with methylated BSA+ OVA." (PMID 33854514, 2021). "The mechanisms by which 20S(OH)D3 downregulates arthritis severity in the CIA model is likely related to reduction in CD4+ T cells, CD19+ B cells, anti-CII antibodies, and maintenance of CD4+CD24+FoxP3+Tregs." (PMID 34276665, 2021). "Subclinical colonic inflammation promotes generation of arthritogenic CD4+ T cells and arthritis development in SKG mice." (PMID 33055428, 2020). "Since effector inflammatory CD4+ T lymphocytes are critical in arthritis progression, we also examined the frequencies of IFN-γ+CD4+ T cells and TNF+CD4+ T cells at two time points of disease development (day 42 and day 95)." (PMID 33072101, 2020). "IGFBP4 (144 ng), with IGFBP6 (85 ng) and 3 (10 ng), was shown to balance the IGF-dependent induction of CD4+FOXP3+ Tregs given by MSC-conditioned medium in arthritis." (PMID 32345351, 2020). "In order to examine changes in the kinetic expression of Clec4b during early arthritis-induction, CD4+ TCR- bead selected splenocytes were isolated from both naïve animals and at different time points after mineral oil injection." (PMID 32497089, 2020). "During the early phases of arthritis, IL‐23R+CD4+CCR6+ T cells were increased in the pLNs of mice and were present in the joints, while IL‐23R+ γδ T cells were not present in the joints at this time point." (PMID 31778214, 2020). "In contrast, Th2 (CD4+IL-4+) and Treg cells (CD4+Foxp3+), known to play critical roles counteracting inflammation in arthritis, were increased only in the late stages of arthritis 19,21." (PMID 32332732, 2020). "A moderate (Spearman r = 0.634) and significant (p < 0.0001) positive correlation was observed between the number of CD4+ T cells in the paws and the arthritis score." (PMID 32966314, 2020). "While mice with lower arthritis scores had fewer number of CD4+ T cells in the paws, a larger percentage of these CD4+ T cells were FoxP3-CD25+." (PMID 32966314, 2020). "During the progressive phase of arthritis, the main infiltrating T cells that were found in the joints of WT mice were CD4+ and γδ T cells, while considerably lower numbers of CD8+ T cells were detected." (PMID 31778214, 2020). "These two molecules are highly expressed in PD-1high MP CD4 T cells from joint synovial tissue of arthritis patients." (PMID 32709717, 2020).
Arthritis (continued). "Colonic CD4+ T cells from mice treated with DSS water induced significantly worse arthritis when compared with colonic CD4+ T cells from mice receiving regular water." (PMID 33055428, 2020). "We found that colonic CD4+ T cells from prearthritic SKG mice induced significantly worse arthritis when compared with splenic CD4+ T cells from the same mice." (PMID 33055428, 2020). "In conclusion, our study demonstrates that IL‐23R+ CD4+CCR6+ T cells are present in the inflamed joints during the early stages of arthritis." (PMID 31778214, 2020). "Intriguingly, all cells in the CFSElow subset were CD4+T cells, which corresponds well with previous findings from the Transfer arthritis model that has described the arthritogenic T cells as mainly CD4+." (PMID 32497089, 2020). "In classical adjuvant arthritis, for example, depletion of CD4+ T cells significantly ameliorates disease even after overt arthritis has been established." (PMID 32345366, 2020). "Paired genotype and DNAm data were available from 141 patients with early arthritis (CD4+ T cells alone in 22 cases, B cells alone in 38, and both cell types in 81)." (PMID 31945409, 2020). "The results showed that inflammatory T cells such as IL-17 + CD4 T cells (Th17) was increased in arthritis-induced M. fascicularis." (PMID 32605610, 2020). "In CD4+Cre RORγ floxed mice arthritis was mitigated, despite continued production of IL-17 by γδ T cells." (PMID 32085540, 2020). "Mice with lower arthritis scores had less CD4+ T cells in the paws, but a larger percentage of cells were FoxP3-CD25+." (PMID 32966314, 2020). "We previously identified a 12-gene CD4+ T cell expression signature in early arthritis patients that predicted a diagnosis of RA." (PMID 30753680, 2019). "IL-18Rα KO mice showed lower arthritis and histological scores in bone erosion and synovitis due to reductions in the infiltration of CD4+ T cells and F4/80+ cells and decreased serum IL-6, -18, TNF, and IFN-γ levels." (PMID 31861496, 2019). "Mice treated with acarbose prior to arthritis induction had significantly increased CD4+CD25+Foxp3+ Treg cells as well as elevation of Helios and CCR6 as demonstrated in both percentage and absolute Treg cell numbers." (PMID 32116681, 2019). "In our study of BD patients with arthritis, CD4+CD62L- and CD8+CD62L- cells in lymphocyte population of active BD patients were significantly increased after improvement compared to the same group of inactive BD patients." (PMID 31614573, 2019). "In a synovial biopsy of a patient with chronic CHIKV-induced arthritis, activated (HLA-DR+) CD4+ T cells were identified as a major cellular infiltrate, but oddly, CD8+ T cells were rarely found." (PMID 31736977, 2019). "This study demonstrates that VD treatment significantly delayed CIA disease onset and decreased the severity of arthritis by downregulating inflammatory Th17 cells while increasing CD4+Foxp3+Nrp-1+ cells." (PMID 30792721, 2019). "For that reason, we aimed to (i) determine the role of maturation in murine dexamethasone and 1α,25-dihydroxyvitamin D3 induced tolDCs and function in arthritis, and (ii) study the effects of tolDCs on CD4+ T cell responses." (PMID 31555285, 2019). "Taken together, these results indicated that rapamycin and DON additively ameliorated arthritis by suppressing CD4+ T cell proliferation and Th17 differentiation in vivo." (PMID 31011190, 2019). "The analysis of T cell populations revealed that arthritis induction increased the number of RORγt+CD4+ T cells, whereas Foxp3+CD4+ T cells and to a lower extent Foxp3+CD8+ T cells were reduced in arthritic controls when compared with naïve mice." (PMID 31394717, 2019). "In this validation study, we confirmed the ability of our previously proposed CD4+ T cell gene expression signature to identify RA patients amongst unselected, treatment-naïve early arthritis clinic attendees." (PMID 30753680, 2019).
Arthritis (continued). "Previous investigation of circulating lymphocytes from early arthritis patients revealed constitutive pSTAT3 levels to be higher, and correlate with paired serum IL-6 concentration more strongly, in CD4+ T cells than in CD8+ T-cells or B-cells." (PMID 31333666, 2019). "Microarray technology was used to measure gene expression in purified peripheral blood CD4+ T cells from treatment-naïve RA patients and disease controls newly recruited from an early arthritis clinic." (PMID 30753680, 2019). "Here we used a mouse model to address two major questions: (i) is a maturation stimulus needed for tolDC function in vitro and in vivo and is maturation required for functioning in experimental arthritis and (ii) can tolDCs modulate CD4+ T cell responses?" (PMID 31555285, 2019). "In an animal model of RA, chimeric mice lacking the B cells producing IL-10 developed severe collagen-induced arthritis with greatly decreased IL-10-secreting CD4 Treg cells and increased Th1 and Th17 cells." (PMID 31554310, 2019). "The initiation of arthritis in SKG mice requires self-reactive (arthritogenic) CD4+ T cells to differentiate into effector Th17 cells and migrate into the joints." (PMID 31497022, 2019). "In a model of collagen-induced arthritis it was described that WT CD4+ T cells secrete more IL-17A when cultured with IL-10 deficient B cells." (PMID 31249364, 2019). "To further determine the contribution of these ILCs to arthritis development, we attempted to selectively deplete ILCs by anti-Thy1.2 mAb in Thy1.2+Rag2−/− mice that had been transferred with CD4+ T cells from Thy1.1+ congenic SKG mice." (PMID 29802020, 2018). "Csf2−/− SKG CD4+ T cells were able to induce autoimmune arthritis in all the recipient mice, although arthritis was significantly less severe than that induced by WT SKG CD4+ T cell transfer." (PMID 29802020, 2018). "We stimulated CD4+ T cells, isolated from spleens of mice with arthritis, with anti-CD3 and increasing doses of IFN-γ." (PMID 29449556, 2018). "The KBN mouse is a spontaneous model of arthritis driven by T cell receptor transgenic CD4+ T cells from the KRN strain that are activated by glucose-6-phosphate isomerase (GPI) peptides presented by the H-2g7 allele from the NOD strain." (PMID 30233578, 2018). "CHIKV arthritis is characterized by an infiltration of large numbers of CD4+ T cells into the joint tissue, and CD4+ T cells are known to be important in CHIKV joint swelling and chronic joint pain." (PMID 30347791, 2018). "Ninety-six days after arthritis induction, spleens and lymph nodes of WT and Ptpn22−/− mice were pooled and assessed for IFNγ+ CD4+ T-cells." (PMID 30054208, 2018). "A low expression of Sema3A in the CD4+ T cells and synovial tissues of RA patients and an alleviation of collagen-induced arthritis by Sema3A overexpression have been previously reported." (PMID 30538782, 2018). "Consistent with the known dependence of arthritis on T lymphocytes, transfer of CD4+ SKG T cells promoted arthritis development in Rag2−/− mice." (PMID 29980684, 2018). "To further assess the possible contribution of GM-CSF from non-CD4 T cells to arthritis development, we transferred Csf2−/− or WT SKG CD4+ T cells into Rag2−/− or Csf2−/−Rag2−/− mice." (PMID 29802020, 2018). "The K/BxN mouse is a spontaneous model of arthritis driven by T cell receptor transgenic CD4+ T cells from the KRN strain that are activated by glucose-6-phosphate isomerase (GPI) peptides presented by the H-2g7 allele from the NOD strain." (PMID 30233578, 2018). "RNA and DNA were isolated from purified B and/or CD4+ T cells obtained from the peripheral blood of 344 patients with early arthritis." (PMID 29193869, 2018). "Transfer of Csf2−/− SKG CD4+ T cells induced histologically evident arthritis in Rag2−/− mice although the arthritis was macroscopically less severe than WT SKG CD4+ T cell transfer." (PMID 29802020, 2018).
Arthritis (continued). "In the case of murine arthritis, naïve CD4+ T-cells were engineered to co-express FOXP3 with HLA-DR1, covalently linked to an immunodominant peptide capable of driving collagen-induced arthritis." (PMID 29503652, 2018). "In spleen samples of animal models, a positive correlation was found between arthritis scores and the percentages of the CD4+CD28−OX40+ T-cell subset (r = 0.5354, P = 0.0004)." (PMID 28320444, 2017). "CD4+ T cells and monocytes/macrophages both play an important role in the pathophysiology of arthritis." (PMID 28173831, 2017). "Using a CD4+ T-cell-dependent model of arthritis, Kcna3−/− rats developed disease similarly to WT rats, indicating that Kv1.3 deficiency did not compromise immune CD4+ T-cell function." (PMID 28248292, 2017). "Heme oxygenase-1 (HO-1) expression in splenic CD4+ T cells isolated from A77 1726-treated arthritis mice were assessed by western blotting." (PMID 28193225, 2017). "The results showed that HO-1 expression in CD4+ T cells of arthritis mice was significantly induced by A77 1726 treatment in a dose-dependent manner." (PMID 28193225, 2017). "The reduced arthritic disease in CHIKV-infected GzmA-/- mice was associated with the reduction of NK cell and T cell infiltrates, with NK cells and CD4 T cells previously shown to promote arthritis in this model." (PMID 28207896, 2017). "It is reported that the production of IL-17 from neutrophils also contributed to the induction of K/BxN arthritis in a CD4 T cell-independent manner." (PMID 28753982, 2017). "Exactly how structural differences in these adjuvant molecules result in different pattern of arthritis induction and arthritogenicity of CD4+ T cells require further investigation." (PMID 29118363, 2017). "MPC treatment 1 day after arthritis induction appeared to greatly limit the recruitment of CD4+ T cells and CD14+ monocytes and macrophages (by around 40%) to the synovium." (PMID 28173831, 2017). "MTX significantly relieved arthritis activity and reduced the percentage of CD4+CD28−OX40+ T cells in PB samples of patients with RA (5.93 ± 1.80% vs 7.74 ± 2.54% posttherapy vs pretherapy, P = 0.038) after 16 weeks of treatment." (PMID 28320444, 2017). "It is known that in arthritis, IL-17-producing CD4 T-helper cells (Th17 cells) are present in the inflamed joint cavity and contribute to the progression of an early inflammation to persistent chronic arthritis." (PMID 29160416, 2017). "Adoptive transfer of CD4+ T cells into infected B6 RAG−/− mice led to exacerbated arthritis and myocarditis, while similar adoptive transfer into B6 TCRα−/− mice resulted in no exacerbated disease and carditis resolution." (PMID 27857714, 2016). "In arthritis, the beneficial effect of gingival derived MSC is associated with an increased frequency of CD4+CD39+Foxp3+ Treg cells and an inhibition on Th1 and Th17 lineages." (PMID 27847522, 2016). "Depletion of CD4+ or CD8+ T cell subsets had little effect on arthritis severity scores, with values similar to WT control-treated mice." (PMID 27857714, 2016). "In proteoglycan-induced arthritis (PGIA), an experimental murine model of arthritis, Treg cell percentage was elevated in B cell-depleted mice, compared to control treated mice that exhibited a higher proportion of CD4+ T cells expressing Foxp3 and CD25." (PMID 27847522, 2016). "The severity of arthritis was reduced in mice that received CD4+CD25+ from LNT-Igk-CII mice compared with those that received CD4+CD25+ Tregs from LNT-Igk-Ctrl mice." (PMID 27301320, 2016). "As SKG Ptpn22−/− mice developed less severe arthritis than SKG mice, we compared cytokine production in peripheral CD4+ T cells in these animals following injection of mannan and induction of arthritis." (PMID 27288531, 2016). "Other populations of CD4+ T cells involved in development or regulation of arthritis, such as Th1 cells and Treg cells, were unaffected by E2." (PMID 25888974, 2015).
Arthritis (continued). "Autoreactive CD4+ T cells and autoantibodies specific for joint tissue are present, and arthritis severity correlates with the number of autoreactive CD4+ T cells and plasmablasts in the joint-draining lymph nodes." (PMID 25963626, 2015). "The frequency of circulating CD146+CD4+ T cells was elevated above normal in some patients with arthritis, correlating with ESR." (PMID 25113810, 2015). "The percentage of proliferating CD4+ T cells correlated with the severity of arthritis, defined by the clinical score (P<0.004, Pearson's correlation)." (PMID 25963626, 2015). "Together, these results show that abatacept is also effective in situations where CD4+ T cell numbers are greatly reduced, suggesting a T cell–independent effect of abatacept that inhibits the progression of arthritis." (PMID 26290328, 2015). "Here, we found that γδ17 cells are the main producers of IL-17 in joints of Il1rn−/− mice, and that recruitment of CCR2+ γδ T cells to the joints via induction of CCL2 by CD4+ T cells is important for the development of arthritis." (PMID 26108163, 2015). "Here we showed that both CD4+ T cells and γδ17 cells are important for development of arthritis in Il1rn−/− mice, because antibody-mediated depletion of either γδ T or CD4+ T cells suppressed the development of arthritis." (PMID 26108163, 2015). "After immunisation with collagen type II and development of arthritis, CD4+ T cell depletion was performed using GK1.5." (PMID 26290328, 2015). "Previously, we have shown that administration of Hsp70 or Hsp70-derived peptides suppresses experimental arthritis via the activation of CD4+CD25+FoxP3+ Tregs." (PMID 26107957, 2015). "CD146+CD4+ T cells accounted, on average, for ≈18%–31% of IL‐17‐producing Th cells, both in arthritis patients and HDs." (PMID 25113810, 2015). "In arthritis patients and controls, IL‐17 production and Th17‐associated surface markers are greatly enriched in CD146+CD4 cells, but the functional repertoire of CD146+CD4 cell populations includes secretion of IL‐22 and IFN‐γ, alone or with IL‐17." (PMID 25113810, 2015). "The increased arthritis from day 4 onwards in μMT mice (which have T cells) is consistent with the arthritogenic role of CHIKV-specific CD4 T cells." (PMID 25474568, 2014). "CD4+ T cells have been implicated in the development of PGIA by observations that anti-CD4 mAb treatment prevents arthritis and that the transfer of the disease requires T cells from arthritic animals." (PMID 24605340, 2014). "When the A12 peptide was administered orally to double-transgenic mice, arthritis was significantly suppressed, despite the fact that >90% of the CD4+ T cells express the Tg." (PMID 24405551, 2014). "The reduction in CD4+ T cells corresponded to the reduction in arthritis severity in p19−/− mice sensitized to antigen by the s.c. route." (PMID 25253467, 2014). "Previous studies have reported that IL-22 is induced in lymphoid organs during arthritis and produced by CD4 T cells and/or CD49b+ cells." (PMID 24676270, 2014). "In the collagen-induced mouse model of RA, intravenous (systemic) transfer of spleen-derived MDSCs was followed by a decrease in the number of CD4+ T cells and reduced arthritis severity in the recipient mice." (PMID 25138129, 2014). "For example, although antibody response plays an essential role in resolution of arthritis, greater roles of CD4+ T cells and iNKT cells as sources of IFNγ are reported in protection and resolution of Lyme carditis." (PMID 24967703, 2014). "Antigen-specific T cells, in particular CD4+ T helper cells, generated within the adaptive immune response initiated through immunisation, play a major role in AIA as arthritis in this model cannot be induced in T cell-deficient mice." (PMID 24491163, 2014). "Altering the route of immunization to the s.c. route that is used in EAE, EAU, and CIA converts PGIA to IL-17-dependent arthritis where both IFNγ-producing and IL-17-producing CD4+ T cells are activated." (PMID 25253467, 2014).